TRGC1 (T cell receptor gamma constant 1)
Description:
Constant region of T cell receptor (TR) gamma chain that participates in the antigen recognition. Gamma-delta TRs recognize a variety of self and foreign non-peptide antigens frequently expressed at the epithelial boundaries between the host and external environment, including endogenous lipids presented by MH-like protein CD1D and phosphoantigens presented by butyrophilin-like molecule BTN3A1. Upon antigen recognition induces rapid, innate-like immune responses involved in pathogen clearance and tissue repair. Binding of gamma-delta TR complex to antigen triggers phosphorylation of immunoreceptor tyrosine-based activation motifs (ITAMs) in the CD3 chains by the LCK and FYN kinases, allowing the recruitment, phosphorylation, and activation of ZAP70 that facilitates phosphorylation of the scaffolding proteins LCP2 and LAT. This lead to the formation of a supramolecular signalosome that recruits the phospholipase PLCG1, resulting in calcium mobilization and ERK activation, ultimately leading to T cell expansion and differentiation into effector cells. Gamma-delta TRs are produced through somatic rearrangement of a limited repertoire of variable (V), diversity (D), and joining (J) genes. The potential diversity of gamma-delta TRs is conferred by the unique ability to rearrange (D) genes in tandem and to utilize all three reading frames. The combinatorial diversity is considerably increased by the sequence exonuclease trimming and random nucleotide (N) region additions which occur during the V-(D)-J rearrangements.
Synonyms: TCRGC1; C1; TCRG
Gene: T-cell receptor constant (C) gene on chromosome 7 (38,257,879 to 38,265,678, reverse strand). Ensembl gene ENSG00000211689.
Subcellular location: Cell membrane
Genetic constraint (gnomAD): Missense variants: 164 observed, 172.83 expected, observed/expected ratio (o/e) 0.95, 90% interval 0.83 to 1.08. Synonymous variants: 52 observed, 56.12 expected, observed/expected ratio (o/e) 0.93, 90% interval 0.74 to 1.17.
Homologues: Paralogues in human: TRGC2 (97% identical), TRGV1 (0% identical), TRGV2 (0% identical), TRGV3 (0% identical), TRGV4 (0% identical), TRGV5 (0% identical), TRGV8 (0% identical).
Diseases named in the same sentence as TRGC1 in open-access papers:
TRGC1 is named in the same sentence as 15 diseases in open-access papers, as found by Europe PMC text mining. Sharing a sentence is not in itself a finding about the gene and the disease. The quoted sentences say what the papers report.
breast carcinoma (1 paper, 2023). "The lower expression of CCL18 and TRGC1 was significantly correlated with favorable survival outcomes in breast cancer, while their higher expression was associated with poor prognosis." (PMID 36805828, 2023). "CCL18 and TRGC1 were highly correlated with survival outcome in breast cancer patients." (PMID 36805828, 2023). "Breast cancer patients with higher expression of CCL18 and TRGC1 had poorer survival." (PMID 36805828, 2023).
vitiligo (1 paper, 2018). Generalized well circumscribed patches of leukoderma that are generally distributed over symmetric body locations and is due to autoimmune destruction of melanocytes. "KLRK1, encoding the activating NK cell receptor NKG2D and TRGC1 that encodes a T cell receptor γ-chain showed a tendency for increased expression in vitiligo lesional skin compared to that in healthy skin (p = 0.055 and p = 0.058, respectively)." (PMID 30515176, 2018). "We could not detect significant upregulation of TRGC1 that encodes a T cell receptor γ-chain arguing against the specific recruitment of γδ T cells to vitiligo lesions." (PMID 30515176, 2018).
tumor (5 papers, 2014 to 2025). "The lower region related to factor 10 that is composed of genes such as H2AFJ, shown to relate to tumor progression in other types of cancer or TRGC1, which may be a marker for higher aggressiveness." (PMID 34638322, 2021).
TRGC1 also shares sentences with these, for which no sentence is quoted: lymphoma (3 papers); cancer (2); T-cell lymphoma (2); T-LGL leukemia (2); B-cell lymphoma (1); blood cancers (1); hematological malignancies (1); infection (1); leukemia (1); lymphoblastic lymphoma (1); lymphoid neoplasm (1); T-cell neoplasms (1).